NUTM2G (NUT family member 2G)
Synonyms: FAM22G; NUTMG
Tractability: No criterion of Open Targets' tractability assessment is met for any kind of drug.
Gene: Protein-coding gene on chromosome 9 (96,928,310 to 96,940,253, forward strand). Ensembl gene ENSG00000188152.
Subcellular location (Human Protein Atlas): Nuclear bodies
Genetic constraint (gnomAD): Loss-of-function variants: 29 observed, 35.44 expected, observed/expected ratio (o/e) 0.82, 90% interval 0.61 to 1.12. The synonymous counts are far from expectation, so gnomAD's model fits this gene poorly and the ratio says little. Missense variants: 495 observed, 726.79 expected, observed/expected ratio (o/e) 0.68, 90% interval 0.63 to 0.73. Synonymous variants: 202 observed, 293.08 expected, observed/expected ratio (o/e) 0.69, 90% interval 0.61 to 0.77.
Homologues: Orthologues: rat Nutm2 (39% identical), mouse Nutm2 (38% identical). Paralogues in human: NUTM2F (99% identical), NUTM2B (84% identical), NUTM2D (84% identical), NUTM2A (84% identical), NUTM2E (84% identical), NUTM1 (48% identical).
Diseases named in the same sentence as NUTM2G in open-access papers:
NUTM2G is named in the same sentence as 2 diseases in open-access papers, as found by Europe PMC text mining. Sharing a sentence is not in itself a finding about the gene and the disease. The quoted sentences say what the papers report.
Alzheimer disease (1 paper, 2021). A progressive, neurodegenerative disease characterized by loss of function and death of nerve cells in several areas of the brain leading to loss of cognitive function such as memory and language. "Genomewide association studies (GWASs) previously linked MROH8 (Maestro heat‐like repeat‐containing protein family member 8) to Alzheimer's disease, whereas the exact function of NUTM2G is not known." (PMID 33778321, 2021).
NUTM2G also shares sentences with these, for which no sentence is quoted: sarcoma (1 paper).